ALDH1B1 (aldehyde dehydrogenase 1 family member B1)
Description:
Broad specificity, mitochondrial aldehyde dehydrogenase that could play a role in the detoxification of alcohol-derived acetaldehyde and other aldehydes. Shows an absolute preference for NAD(+) as no activity is detected with NADP(+). Has a high affinity and catalytic efficiency toward aliphatic medium-chain saturated aldehydes relative to short-chain and aromatic aldehydes in vitro. Also capable of metabolizing products of lipid peroxidation, namely 4-hydroxynon-2-enal(4-HNE) and malonaldehyde (MDA) but with lower catalytic efficiency. In vitro, it can also display a nitroglycerin reductase activity. Has also an esterase activity in vitro, but this may be not physiologically relevant in vivo.
Synonyms: ALDH5; ALDHX
Tractability: Small molecule: a structure with a bound ligand is known; a high-quality ligand is known; it belongs to a druggable protein family. PROTAC: ubiquitination databases record sites on it; its protein half-life has been measured; a small molecule that binds it is known.
Target class: Enzyme; Oxidoreductase
Gene: Protein-coding gene on chromosome 9 (38,392,623 to 38,398,661, forward strand). Ensembl gene ENSG00000137124.
Subcellular location: Mitochondrion matrix
Subcellular location (Human Protein Atlas): Mitochondria
Pathways (Reactome):
Metabolism: Ethanol oxidation
Metabolism of proteins: Mitochondrial protein degradation
Gene Ontology:
Molecular function: acetaldehyde dehydrogenase (NAD+) activity; aldehyde dehydrogenase (NAD+) activity; benzaldehyde dehydrogenase (NAD+) activity; oxidoreductase activity, acting on other nitrogenous compounds as donors, with NAD or NADP as acceptor; retinal dehydrogenase (NAD+) activity; NAD binding; medium-chain fatty aldehyde dehydrogenase (NAD+) activity; oxidoreductase activity
Biological process: aldehyde metabolic process; ethanol catabolic process
Cellular component: mitochondrion; mitochondrial matrix; cytosol
Genetic constraint (gnomAD): Loss-of-function variants: 22 observed, 30.51 expected, observed/expected ratio (o/e) 0.72, 90% interval 0.51 to 1.03. The upper end of that interval is the gene's LOEUF score, 1.03, which puts it in group 4 of 6, group 1 being the genes least tolerant of losing a copy. Missense variants: 671 observed, 715.04 expected, observed/expected ratio (o/e) 0.94, 90% interval 0.88 to 1. Synonymous variants: 249 observed, 298.04 expected, observed/expected ratio (o/e) 0.84, 90% interval 0.75 to 0.93.
Homologues: Orthologues: chimpanzee ALDH1B1 (99% identical), macaque ALDH1B1 (98% identical), dog ALDH1B1 (95% identical), pig ALDH1B1 (94% identical), mouse Aldh1b1 (94% identical), rat Aldh1b1 (94% identical), tropical clawed frog aldh1b1 (77% identical), Caenorhabditis elegans alh-1 (63% identical), Caenorhabditis elegans alh-2 (62% identical), Drosophila melanogaster CG31075 (56% identical), Drosophila melanogaster CG8665 (45% identical), Caenorhabditis elegans alh-3 (45% identical), and 3 more. Paralogues in human: ALDH2 (74% identical), ALDH1A2 (65% identical), ALDH1A1 (62% identical), ALDH1A3 (62% identical), ALDH1L1 (49% identical), ALDH1L2 (49% identical), ALDH9A1 (39% identical), ALDH8A1 (35% identical), ALDH5A1 (33% identical), ALDH7A1 (30% identical), ALDH6A1 (30% identical), ALDH4A1 (27% identical), and 5 more.
Diseases named in the same sentence as ALDH1B1 in open-access papers:
ALDH1B1 is named in the same sentence as 63 diseases in open-access papers, as found by Europe PMC text mining. Sharing a sentence is not in itself a finding about the gene and the disease. The quoted sentences say what the papers report.
colon cancer (14 papers, 2015 to 2024). "Further studies have demonstrated that ALDH1B1 is associated with diabetes, colon cancer, pancreatic cancer and osteosarcoma." (PMID 35805102, 2022). "Further studies have demonstrated that ALDH1B1 is associated with diabetes, colon cancer, pancreatic cancer and osteosarcoma, as well as in regulating different CSC-related signaling pathways, such as PI3K/Akt, Notch and Wnt/β-catenin." (PMID 33419031, 2021). "Because Wnt-signaling activation and ALDH1B1 expression appear to be closely linked in human colon cancer and ApcMin mice, we examined the effect of ALDH1B1 knockdown on Wnt/β-catenin signaling." (PMID 25950950, 2015). "Recently, guanidinyl antagonists of ALDHs (IGUANAs) were discovered as specific inhibitors of ALDH1B1 with efficient potency against cancer cells in preclinical studies, inducing selective growth inhibition of colon cancer spheroids and organoids." (PMID 39408636, 2024). "Editors' choice: Increased acetaldehyde levels are associated with acceleration of defective mismatch repair-driven colonic tumour development in models of Lynch syndrome with inactivated Aldh1b1, involving DNA damage responses and decreased apoptosis." (PMID 37395714, 2023). "Aldehyde dehydrogenase 1B1 (ALDH1B1) is an isoform that has been characterized as a marker of colon cancer progression, while various studies suggest its importance in additional malignancies." (PMID 36676146, 2023). "Given the well-established significance of ALDH1B1 in colon cancer, studies have now started to focus on how to accomplish its inhibition in order to enhance the efficiency of current therapeutic protocols." (PMID 36676146, 2023). "Aldehyde dehydrogenase 1B1 (ALDH1B1) has been correlated with colorectal tumorigenesis and is considered a potential biomarker for colon cancer." (PMID 35805102, 2022). "Human colon cancer HT29 cells were stably transfected either with human green fluorescent protein (GFP)-tagged ALDH1B1 or with an empty lentiviral expression vector." (PMID 33419031, 2021). "The depletion of ALDH1B1 in colon cancer cells resulted in the downregulation of Wnt/β-catenin, Notch, and PI3K/Akt pathway-related genes such as CTNNB1, Akt, and Notch1." (PMID 34769507, 2021). "ALDH1B1, apart from being a potential colon cancer biomarker, was also shown to be crucial for tumor development by modulating canonical Wnt/β-catenin, Notch and PI3K/Akt signaling pathways." (PMID 33419031, 2021). "Knockdown of ALDH1B1 greatly reduced the prevalence of ALDHbright cells, showing that ALDH1B1 was responsible for the high ALDH activity of ALDHbright SW480 colon cancer cells." (PMID 25950950, 2015). "Luciferase activity was measured to determine the basal level of activation of the promoters for ALDH1B1 and c-Myc in these colon cancer cells." (PMID 25950950, 2015). "Given that ALDHbright cells are considered to possess high tumorigenic potential, the results are consistent with ALDH1B1 playing an important role in tumorigenesis of colon cancer cells." (PMID 25950950, 2015). "High levels of ALDH1B1 in human colon cancer cells are suggestive of a role for ALDH1B1 in colon tumorigenesis." (PMID 25950950, 2015). "ALDH1B1 is particularly significant as a biomarker for colon cancer." (PMID 39408636, 2024). "In this context, the selective suppression of ALDH1B1 and/or the use of specific ALDH1B1 inhibitors may be promising approaches for CSC-directed therapeutics in colon cancer." (PMID 35805102, 2022). "In addition, the depletion of ALDH1B1 in colon cancer cells affected the Wnt/β-catenin pathway, which has central roles in normal stem cells and CSCs." (PMID 34769507, 2021).
colon cancer (continued). "This speculation is supported by several pieces of evidence, demonstrating a specific elevated expression of ALDH1B1 in colon cancer; ALDH3B1 in lung, breast, ovarian, and colon cancer; ALDH3A1 in lung cancer; and ALDH7A1 in prostate cancer." (PMID 35582039, 2020). "Next, we hypothesized that ALDH1B1 affected colon cancer formation by modulating Wnt/β-catenin signaling in colon cancer cells." (PMID 25950950, 2015). "Our findings demonstrate that ALDH1B1 may not only be a potential biomarker for colon cancer but also play a functional role in the formation of tumors in colorectal cancer." (PMID 25950950, 2015). "In summary, our data demonstrate that ALDH1B1 may promote colon cancer tumorigenesis by modulating the Wnt/β-catenin, Notch and PI3K/Akt signaling pathways." (PMID 25950950, 2015). "As such, ALDH1B1 may be one of the factors imparting high tumorigenicity to these tumor-initiating cells in colon cancer." (PMID 25950950, 2015). "On the basis of our findings, it may be proposed that ALDH1B1 has a pro-tumorigenic role in human colon cancer cells." (PMID 25950950, 2015). "In addition, we demonstrated that the ALDH1B1 promoter was transcriptionally active in colon cancer cell lines." (PMID 25950950, 2015). "We demonstrated that, in addition to acting as a potential colon cancer biomarker, ALDH1B1 may significantly contribute to the development of tumors by modulating canonical Wnt/β-catenin, Notch and PI3K/Akt signaling pathways." (PMID 25950950, 2015). "Selective targeting of ALDH1B1 may represent a novel means to prevent or treat colon cancer." (PMID 25950950, 2015). "Both ALDH1B1 and ALDH2 were expressed in all the cell lines tested, suggesting they play a crucial role in colon cancer." (PMID 36676146, 2023). "In colon cancer, ALDH1B1 is dramatically upregulated, and by up-regulating Wnt/β-Catenin, Notch and PI3K/Akt signaling pathways, ALDH1B1 can promote colon cancer tumorigenesis, providing a novel target to prevent or treat colon cancer." (PMID 27015121, 2016). "Taken together, these findings indicate that ALDH1B1 positively modulates Wnt/β-catenin and Notch signaling pathways in SW480 colon cancer cells." (PMID 25950950, 2015). "To examine this possibility, we used an shRNA approach to suppress or knock down expression of ALDH1B1 in SW480 cells, a human colon cancer cell line." (PMID 25950950, 2015). "It has been previously shown that ALDH1B1 could promote colon cancer tumorigenesis by modulating the Wnt/β-catenin, Notch and PI3K/Akt signaling pathways and might be considered as a selective therapeutic targets to prevent or treat colon cancer." (PMID 29416787, 2018). "Given the ALDH1B1-driven cell cycle attenuation at the G2/M phase, and chemoresistance against DNA-damage agents previously observed in human colorectal adenocarcinoma cells, we hypothesize that ALDH1B1 plays an important role in DDR mechanisms and the development of colon cancer." (PMID 35805102, 2022). "With our discovery that ALDH1B1 may be central for colon cancer formation and is a major contributor of ALDH activity in highly tumorigenic ALDHbright SW480 colon cancer cells, we examined the relationship between ALDH1B1 and the Wnt/β-catenin signaling pathway." (PMID 25950950, 2015).
colorectal cancer (9 papers, 2015 to 2025). A primary or metastatic malignant neoplasm that affects the colon or rectum. "A substantial number of studies are available on the association of ALDH1B1 and colorectal cancer, mainly investigating tumor expression and, in certain cases, in comparison to the respective non-cancerous tissues." (PMID 36676146, 2023). "Our results show that PI3K/Akt pathway is down-regulated upon ALDH1B1 suppression, possibly by down-regulating PPARβ/δ which corroborates earlier findings and suggests an association between this pathway and colorectal cancers." (PMID 25950950, 2015). "Along with this, there is evidence linking ALDH1B1 with colorectal cancer stemness, resulting in chemotherapy resistance." (PMID 37686694, 2023). "According to the study, the knockdown of ALDH1B1 in colorectal cancer cells resulted in a reduction in CTNNB1 (β-catenin) mRNA levels." (PMID 34769507, 2021). "A recent study showed that ALDH1B1 modulates the Wnt/β-catenin pathway, which is crucial for colorectal cancer formation." (PMID 34769507, 2021). "In a clinical study, the upregulation of ALDH1B1 was correlated with high-grade colorectal carcinoma and the presence of lymph-node metastases, implying a potential role of ALDH1B1 in carcinogenesis." (PMID 34769507, 2021). "ALDH1 is abundant in tumor samples from patients with CRC, which can be used as a particular marker for CSCs of colorectal cancer, mainly including ALDH1A1, ALDH1B1, and ALDH1A3, are associated with poor prognosis and resistance to chemotherapy in colorectal cancer." (PMID 36387165, 2022). "A recent study revealed that genes associated with intestinal stem cells could be used to predict relapse in colorectal cancer patients, one of which was ALDH1B1, a well-known marker of intestinal stem cells and colorectal CSCs." (PMID 34769507, 2021). "ALDH1A1 and ALDH1B1 were shown to be markers for colorectal cancer." (PMID 32377192, 2020). "To validate the effects of JIB-04 on the mRNA expression of β-catenin target genes, we measured the mRNA levels of CSC-associated genes (CD44, LGR5, DKK1, ALDH1A3, ALDH1B1, CD24, and SOX4) by qRT-PCR in three different colorectal cancer cell lines after treament with JIB-04." (PMID 29700375, 2018). "Collectively, these findings suggest that ALDH1B1 may modulate colorectal cancer formation through a mechanism involving the Wnt/β-catenin signaling pathway." (PMID 25950950, 2015). "As a result, ALDH1B1 may serve as yet another marker for colorectal cancer." (PMID 37686694, 2023). "Among the available colorectal cancer cell lines, HCT116 cells were selected for studying ALDH1B1 enzyme activity because these cells constitutively and highly express ALDH1B1, while they show low ALDH1A1 expression." (PMID 34769507, 2021). "As AMBRA1 affected CTNNB1 transcription via ALDH1B1, which is a crucial CSC marker of colorectal cancer, we next investigated whether AMBRA1 expression affects the mRNA levels of several CSC-related β-catenin target genes, including LGR5, HIF1a, ALDH1A3, CD24, and SOX4." (PMID 34769507, 2021).
diabetes (6 papers, 2010 to 2023). "ALDH1B1 was found upregulated in the injured pancreas after streptozotocin paradigms and showed an association with diabetes." (PMID 36686487, 2022). "generated global Aldh1b1 knockout mice that have an increase in blood acetaldehyde levels and blood glucose levels, indicating that Aldh1b1 has a potentially pivotal role in the link between alcohol consumption and diabetes." (PMID 36694633, 2023). "The relationship of this ALDH2 variant as well as the ADH7 and ALDH1b1 variants with diabetes and CHD related phenotypes have not been studied previously, except from a previous study (n = 1,216) from our group." (PMID 20700531, 2010).
pancreatic cancer (5 papers, 2021 to 2023). "Studies showed that loss of function of this enzyme induces deficiency in mouse ß-cells and upregulation of ALDH1B1 enzyme was identified in human pancreatic cancer." (PMID 37529091, 2022). "ALDH1B1 is abundantly expressed in human pancreatic cancer and the high expression of ALDH1B1 contributes to cancer progression and dreadful prognosis." (PMID 36694633, 2023). "Moreover, studies have reported that ALDH1B1 could be a novel biomarker for detecting colorectal cancer and may be a modulator of pancreatic cancer." (PMID 35805102, 2022). "A growing number of studies have revealed that the aberrant expression of ALDH1B1 has been observed in several human cancers such as CRC,154 pancreatic cancer, NSCLC,135 GC, and HCC,155 and it is involved in tumorigenesis and metastasis as well as clinical prognosis." (PMID 36694633, 2023).
breast carcinoma (4 papers, 2015 to 2026). "The review of the literature connects downregulation of ALDH1B1 to numerous cancers including colorectal, pancreatic, liver, prostate, lung, brain, and breast cancers to name a few." (PMID 38584916, 2024). "To gain clinical significance, using The Cancer Genomic Atlas (TCGA) breast cancer cohort, we dichotomized 1082 breast cancer subjects into two groups based on the expression of the seven genes (ALDH1B1, ASTL, CA7, CPLX4, KCNV2, MAGEE2 and TUBA3E)." (PMID 28487351, 2017). "Top HBF + BPA-dysregulated genes (ALDH1B1, ASTL, CA7, CPLX4, KCNV2, MAGEE2 and TUBA3E) are associated with poor overall survival in The Cancer Genomic Atlas (TCGA) human breast cancer cohort (n = 1082)." (PMID 28487351, 2017). "Utilizing the public CRISPR knockout screening datasets sourced from DepMap, we further supported our hypothesis that the essential roles of ADH5, ALDH1B1, and ALDH7A1 in breast cancer cell growth and development." (PMID 42196229, 2026). "We took advantage of the publicly available RNA-seq and survival data from TCGA and determined that seven differentially expressed genes (ALDH1B1, ASTL, CA7, CPLX4, KCNV2, MAGEE2 and TUBA3E) could be involved in breast cancer development, especially in Caucasian female patients with ER positivity." (PMID 28487351, 2017). "Interestingly, expression of four genes (ALDH1B1, ASTL, CA7 and TUBA3E) of the seven gene panel was significantly different between the two groups of human breast cancer subjects (data not shown)." (PMID 28487351, 2017).
osteosarcoma (4 papers, 2018 to 2023). A usually aggressive malignant bone-forming mesenchymal neoplasm, predominantly affecting adolescents and young adults. "In conclusion, our study demonstrates that ALDH1B1 is overexpressed and significantly correlated with poor prognosis of osteosarcoma patients." (PMID 29416787, 2018). "Thus, both wound healing assay and matrigel invasion assay revealed that the inhibition of ALDH1B1 expression by siRNA transfection significantly suppressed the migration and invasion of osteosarcoma cells." (PMID 29416787, 2018). "Moreover, ALDH1B1 is essential for osteosarcoma cell growth and survival in vitro and in vivo while promote apoptosis and cell cycle arrest in vitro." (PMID 29416787, 2018). "Another study of the same group demonstrated that ALDH1B1 is negatively regulated by microRNA-761; miR-761 appeared to suppress tumor formation in the xenograft models and regulate cell adhesion, EMT, and TGF-β by targeting ALDH1B1 in osteosarcoma." (PMID 36676146, 2023). "Furthermore, the high ALDH1B1 expression was significantly correlated with overall survival, tumor metastasis and TNM stages of osteosarcoma patients." (PMID 29416787, 2018).
colon adenocarcinoma (3 papers, 2015 to 2023). "The main aim of our study was to explore the potential effect of ALDH1B1 in human colon adenocarcinoma." (PMID 33419031, 2021). "In this study, we investigated the role of ALDH1B1 in the pathophysiology of human colon adenocarcinoma." (PMID 33419031, 2021). "In contrast, extremely high ALDH1B1 expression was observed throughout the cells of human colon adenocarcinomas." (PMID 25950950, 2015).
colorectal adenocarcinoma (3 papers, 2021 to 2024). The most common type of colorectal carcinoma. "We demonstrated that ALDH1B1 induced cell morphological changes in A549 cells, which is in line with our previous observations of ALDH1B1-induced morphological alterations in human colorectal adenocarcinoma (HT29) cells." (PMID 39408636, 2024). "The present study examines the role of ALDH1B1 in DNA damage response (DDR) in human colorectal adenocarcinoma." (PMID 35805102, 2022). "In this study, the pathophysiological role of ALDH1B1 in human colorectal adenocarcinoma was investigated." (PMID 33419031, 2021). "The potential enhanced DDR of ALDH1B1-overexpressing colorectal adenocarcinoma cells may be one of the mechanisms that can relate with the cancer stem-like phenotype previously reported for ALDH1B1-overexpressing HT29 and CaCo2 cells." (PMID 35805102, 2022).